CDK6 (cyclin dependent kinase 6)
Diseases named in the same sentence as CDK6 in open-access papers (continued):
Sharing a sentence is not in itself a finding about the gene and the disease.
breast cancer (continued). "CNA of CDK6 on the other hand predicted a worse prognosis in the brain and a good prognosis of breast cancer cohorts." (PMID 33668805, 2021). "On the other hand, several lines of evidence have shown that increased CDK6 protein levels conferred breast cancer cells with resistance to CDK4/6i treatment." (PMID 34508104, 2021). "hsa_circ_0136666 promotes breast cancer cell proliferation and induces G2/M phase transition by sponging miR‐1299 and up‐regulating CDK6 expression." (PMID 34672397, 2021). "miR-29b-3p exerted its antiproliferative effect via negative regulation of CDK6 in breast cancer cell lines." (PMID 34439268, 2021). "Accordingly, pharmacological inhibition of Cdk4 and Cdk6 prevented tumor development in mouse models of breast cancer, sustained by cyclin D1, and leukemia, sustained by cyclin D3." (PMID 34204543, 2021). "Altogether, these results demonstrate that RB1 and CDK6 play a pivotal role in determining the cellular sensitivity of breast cancer cells to CDK4/6i." (PMID 34508104, 2021). "We then confirmed the observation that exposure of MCF7 and MDA-MB-231 breast cancer cells to ribociclib facilitated CDK6 protein accumulation in a time-dependent manner." (PMID 34508104, 2021). "The expanding clinical application of CDK4- and CDK6-inhibiting drugs in the managements of breast cancer has raised a great interest in testing these drugs in other neoplasms." (PMID 34445095, 2021). "Cyclin-dependent kinase 6 (CDK6) inhibitors are the most widely used treatment options in breast cancer patients." (PMID 34722544, 2021). "Upregulation of CDK6 as a result of gene amplification has been reported in abemaciclib-resistant breast cancer cell lines in which knockdown of CDK6 restored sensitivity to abemaciclib." (PMID 33671468, 2021). "The recent addition of cyclin-dependent kinase 4 (CDK4) and CDK6 inhibitors (palbociclib, ribociclib, abemaciclib) to endocrine therapy have remarkably improved the outcome of patients with HR+ advanced breast cancer." (PMID 33477469, 2021). "CDK6 expression was positively correlated with macrophages only in breast cancer (BRCA), liver hepatocellular carcinoma (LIHC), and lung adenocarcinomas (LUADs)." (PMID 33668805, 2021). "Palbociclib and ribociclib are two CDK4/CDK6 inhibitors permitted for clinical use in these breast cancer treatments, combined with fulvestrant or letrozole." (PMID 34361615, 2021). "Although the efficacy of combining HT and CDK4 and CDK6 inhibitor in patients with ESR1+/HER2− breast cancer, the promising benefit of CDK4 and CDK6 drug inhibitors in other neoplasms has not been extensively tested." (PMID 34445095, 2021). "As a proof-of-concept, focused follow-up studies silencing either RB1 or CDK6 led to significant alteration of drug sensitivity of MCF7 breast cancer cells to CDK4/6i, supporting the reliability of our in vitro screening results." (PMID 34508104, 2021). "Targeting Cyclin-dependent Kinase 4 (CDK4) and Cyclin-dependent Kinase 6 (CDK6) in ER+ breast cancer is useful because these cancers often have the cyclin D1–CDK4/6–Rb pathway activated." (PMID 34830174, 2021). "Cell-based expression and therapeutic evaluation showed that EA treatment decreases the expression of CDK6, inhibited cell proliferation, and induces apoptosis in the breast cancer cells." (PMID 32429317, 2020). "The co‐treatment with CDK4/CDK6 and AKT inhibitors demonstrated the inhibition of RB‐positive, but RB‐deficient, breast cancer cells." (PMID 32508030, 2020). "Intriguingly, the expression of cdk4, cdk6, e2f1, and rb1 in breast cancer was moderate or low compared to that in all tumors." (PMID 32357912, 2020). "Apart from non-selective agents that block CDKs, small molecular weight inhibitors with dual specificity for the close homologues CDK4 and CDK6 have been FDA approved for the treatment of breast cancer." (PMID 33255177, 2020).
breast cancer (continued). "Based on the data presented above, we have defined a signaling axis that c-myc downregulates miR-29b-3p to promote activation of CDK6, thus inducing palbociclib resistance in breast cancer." (PMID 32934206, 2020). "Apart from breast cancer cells, BA was reported to suppress the cell cycle progression and proliferation of prostate cancer cells through the CDK6/FOXM1 axis." (PMID 32625089, 2020). "In summary, LMWE appears to be predictive in sensitivity for the combination of CDK4/CDK6 inhibitors with autophagy targeting in advanced ER+ breast cancer." (PMID 32878084, 2020). "Its upregulation promoted glycolysis, was associated with cytosolic CDK6, and regulated the CDK6-dependent phosphorylation of fructose bisphosphatase PFK2, thus defining a functional role for this lncRNA in metabolic reprogramming in breast cancer." (PMID 32765426, 2020). "CDK4/CDK6/cyclin D signaling is altered in 35% of ER+ breast cancer patients, but 16% of patients fail to respond to the treatment." (PMID 32878084, 2020). "Nar isolated from Thymus vulgaris upregulated pro-apoptotic markers, p18, p19, p21, Bax and Bak, and downregulated anti-apoptotic markers, Cdk4, Cdk6, Cdk7, and Bcl-2 in human colorectal and breast cancer cells leading to apoptosis." (PMID 33192517, 2020). "They identified that some genes like MTDH, IGF1R and CDK6 can be affected by miRNAs and can modify cellular processes in breast cancer." (PMID 32635415, 2020). "Amplifications of CDK6 were also found in breast cancer cell lines with acquired abemaciclib resistance and knock-down of CDK6 was sufficient to restore sensitivity." (PMID 33255177, 2020). "In a breast cancer model, through its direct interaction with its mRNA targets CDK6, SIRT1 and Sp1, which are genes involved in senescence, miR-22 has been able to suppress tumor growth." (PMID 31640796, 2019). "The inhibition of cell cycle regulators such as CDK4 and CDK6 has become a new therapeutic frontier for the treatment of breast cancer (BC)." (PMID 31506466, 2019). "The adverse impacts of CDK6 have been investigated in most gynecologic tumors, including epithelial ovarian cancer and breast cancer, and its activity is always considered as an important point for tumor inhibition during clinical treatment." (PMID 30829464, 2019). "We found that individual treatment with BET or CDK6 inhibitors have only a mild suppressive effect on proliferation and survival of luminal breast cancer." (PMID 30518851, 2018). "Cdk6 can have a role as tumor suppressor reducing proliferation in lymphoid malignancies, or restrain the proliferation of breast cancer cells." (PMID 29875623, 2018). "Here our study discovered the novel role of FOXO3a/BRD4/CDK6 axis in AKTi resistance of luminal breast cancer cells." (PMID 30518851, 2018). "This suggests that MK2206-mediated CDK6 upregulation is specific to luminal subtype of breast cancer." (PMID 30518851, 2018). "The CDK6 induction by FOXO3a/BRD4 is responsible for tumor cell survival because overexpression of CDK6 in luminal breast cancer cells significantly relieves AKTi-induced cell growth arrest and apoptosis." (PMID 30518851, 2018). "For example, troglitazone induced G1 arrest and apoptosis by reducing the expression of cyclin D1 and CDK6 in breast cancer cells." (PMID 30018246, 2018). "Here, the authors demonstrate that BRD4/FOXO3a axis upregulates CDK6 promoter activity to promote resistance to AKT inhibition in breast cancer cells and that blocking the action of CDK6 re-sensitizes resistant cancer cells to growth inhibition." (PMID 30518851, 2018). "Clearly, CDK6 are now well known for downregulating the growth of breast cancer cells, suggesting a potential tumor-suppressing mechanism of PARKIN on breast cancer cells." (PMID 30274236, 2018). "Our study reports the involvement of BRD4/FOXO3a/CDK6 axis in AKTi resistance and provides potential therapeutic strategies for treating resistant breast cancer." (PMID 30518851, 2018).
breast cancer (continued). "Although this study determined the relevance of DLC1 in breast cancer within a subset population of CDK6 interaction, our study suggests the importance of DLC1 in ER-positive breast cancer regardless of other factors." (PMID 30278072, 2018). "To interrogate the biological effect of downregulating these proteins, we knocked down CDK4 and/or CDK6 in two ER+ breast cancer cell lines, MCF7 and T47D via shRNA and siRNA." (PMID 28653662, 2017). "Together, the data show that abemaciclib is a CDK4 and CDK6 inhibitor that demonstrates both in vitro and in vivo antitumor activity in breast cancer models." (PMID 29050219, 2017). "InuA upregulated the expression of p21 and Bax, induced the cleavage of PARP, and reduced the expression of Cdk2, Cdk4, Cdk6, Cyclin D1, Cyclin E, c-Myc, and Bcl2 in both breast cancer cell lines." (PMID 27105525, 2016). "We found that expression levels of the known cell cycle-regulating miR-34 targets CCND1, CDK4 and CDK6, were downregulated upon miR-34c expression in breast cancer cell lines." (PMID 25064703, 2014). "We are the first to report such synergistic effects of DLC1 and CDK6 on breast cancer survival at the transcriptional level, the overdominant model fitted by the SNP pair, and the dominant negative effect at the translational level." (PMID 25425654, 2014). "(-)-Oleocanthal treatment was shown to reduce expression of cyclin D1 and CDK6, and caused a corresponding increase in p21 and p27 levels in MDA-MB-231 breast cancer cells." (PMID 24849787, 2014). "Here, we explore the functional relations between DLC1 and CDK6 in breast cancer survival at both germ line genetic and gene expression levels." (PMID 25425654, 2014). "Here, we explore the influence of the synergistic effect of DLC1 and CDK6 on human breast cancer survival at the genetic, transcriptional, and translational levels." (PMID 25425654, 2014). "The results help us in understanding the cooperation between DLC1 and CDK6 in breast cancer, which, once experimentally verified, contribute to personalized medicine and can be applied for clinical use." (PMID 25425654, 2014). "The gene expression of DLC1 is positively influenced by that of CDK6 in ER-positive breast tumors, indicating the importance of ER in the interactions between DLC1 and CDK6 in breast cancer." (PMID 25425654, 2014). "A recent study indicated that CDK6, as a key protein, coordinated cell proliferation and migration in breast cancer mainly dependent on the expression of estrogen receptor." (PMID 25178497, 2014). "CDK6 overexpressed in several malignancies (including breast cancer, lymphoma and melanoma) has been demonstrated to be involved in leukemic cell differentiation block." (PMID 22384175, 2012). "It seems that the common down-regulation of the miR-200 family and the miR-183-96-182 cluster results in the activities of WNT signaling and CDK6, which can control breast cancer stem cell differentiation and self-renewal to allow malignant proliferation." (PMID 22384175, 2012). "In addition, CP-10 was tested in two independent palbociclib-resistant breast cancer cell lines with CDK6 copy amplification (MCF-7 CDK6N2) and FAT1 loss (MCF-7 FAT1 CR), where it successfully induced CDK6 degradation and inhibited proliferation." (PMID 40793752, 2025). "CDK4 and CDK6 inhibitors that target cell cycle mechanisms have already been introduced into the clinic and used to treat breast cancer, and may have a profound impact on targeted therapies for other tumor types (Álvarez-Fernández and Malumbres, 2020)." (PMID 40303979, 2025). "Recent findings have highlighted the role of N6-methyladenosine (m6A) modification in ER+ breast cancer, particularly its capacity to regulate mRNA dynamics, such as the expression of CDK6, a critical mediator in cell cycle progression and a known target of CDK4/6 inhibitors." (PMID 40303916, 2025).
breast cancer (continued). "Among them, ATF-2 demonstrated antiproliferative activity comparable to HER2 inhibitor lapatinib and significantly suppressed HER2 expression and activity, epidermal growth factor receptor (EGFR) activity, and cyclin-dependent kinase 6 (CDK6) expression in HCC1954 breast cancer cells." (PMID 41537091, 2025). "Others demonstrated that abemaciclib (CDK4/CDK6 inhibitor) significantly enhanced anti-tumor responses in cell lines, animal models and breast cancer patients by increasing the capacity of tumor cells to present antigen and reducing Treg levels resulting in decreased Treg/CD8 T-cell ratio." (PMID 39007281, 2024). "Hence, high levels of cyclin D1, CDK4, and CDK6 are often observed in most patients with breast cancer." (PMID 39328201, 2024). "Indeed, it has been shown that activated GR binds to and represses the enhancer regions of the ER-mediated cell cycle genes’ (e.g., CCND1, CDK2, and CDK6) in ER+ breast cancer cells." (PMID 39519365, 2024). "Established breast cancer targets CDK6 and EGFR also show high-amplitude rhythms." (PMID 38319971, 2024). "In breast cancer cells expressing high levels of CDK4, we confirm this hypothesis and develop a high-throughput compatible assay that quantifies genetically modified CDK6 variants and inhibitors." (PMID 36884374, 2023). "A recent study suggests that CDK6-deficient cancer cells that rely on the function of CDK4 in cell cycle progression are sensitive to these inhibitors; in contrast, upregulation of CDK6 in breast cancer cells promotes CDK4/6 inhibitor resistance." (PMID 37744274, 2023). "Cyclin D1, frequently over-expressed in ESR1-mutated breast cancer, could activate the CDK4 and CDK6 to facilitate cell cycle progression through the G1 restriction point." (PMID 36624500, 2023). "We discussed some applications of CDK6 in breast cancer, melanoma, and hemorrhagic malignancies." (PMID 36457244, 2023). "This is somehow intriguing, as RAS G12V has not been associated with resistance against CDK4/CDK6 inhibitors in the context of breast cancer or other malignancies." (PMID 35804842, 2022). "CDK6 has been shown to play an important role in regulating cell cycle progression and the up-regulation of CDK6 activity is closely related to the occurrence and development of multiple types of cancer, including breast cancer, hematological malignancies, and several solid tumors." (PMID 35480115, 2022). "Therefore, small molecule inhibitors of CDK6 have been officially approved or clinically tested to act against cancers including breast cancer, lymphoma, and multiple myeloma." (PMID 35589670, 2022). "Repression of CDK4 and CDK6 levels by miR-138 has been demonstrated in breast cancer cell lines." (PMID 34937878, 2022). "In support of this, it was reported that CDK6 inhibition using Quercetin had no negative effect on viability of breast cancer and human adenocarcinoma cells, associating with induction of apoptosis." (PMID 36619863, 2022). "Additionally, abnormal CDK6 expression has been detected in breast cancer, pancreatic cancer, malignant glioma, and medulloblastoma." (PMID 34249735, 2021). "Furthermore, we show that CDK4/6i treatment can alter the protein levels of RB1 and CDK6 to confer breast cancer cells with acquisition of CDK4/6i resistance." (PMID 34508104, 2021). "Interestingly, it has been demonstrated that the increased CDK6 expression observed in CDK4/6i-resistant breast cancer cell models is dependent on the suppression of the TGF-β pathway by the miR-432-5p expression." (PMID 34771560, 2021). "Copy number (CN) alterations in ctDNA were also associated with breast cancer subtype, with CN alterations in MYC, PIK3CA, EGFR, CCNE1, CDK6, BRAF and MET more common in TNBC (q = 0.01, q < 0.0001, q = 0.001, q < 0.0001, q = 0.0003, q = 0.0002 and q = 0.01, respectively)." (PMID 33893289, 2021).
breast cancer (continued). "Correlation analyses also indicated that CDK4 expression was positively correlated with expressions of CDK2 and CDK6 in liver cancer, lung cancer, prostate cancer, pancreatic cancer, melanoma, head and neck cancer, glioblastoma, breast cancer, and cervical cancer cohorts (r = 0.06~0.69)." (PMID 33668805, 2021). "Of note, genomic amplification of the CDK6 locus was observed in breast cancer." (PMID 34508104, 2021). "Ribociclib (7-cyclopentyl-N,N-dimethyl-2-[(5-piperazin-1-ylpyridin-2-yl)amino]pyrrolo[2,3-d]pyrimidine-6-carboxamide) is also an FDA-approved CDK4/CDK6 inhibitor combined with a fulvestrant or aromatase inhibitor for ER-positive/HER2-negative advanced breast cancer treatment in postmenopausal women." (PMID 34361615, 2021). "Both lncRNA YIYA and CDK6 are required to maintain enhanced glycolysis in breast cancer." (PMID 33652661, 2021). "CDK6, which is a member of the family of cyclin-dependent kinases, has been identified as a tumor oncogene that was upregulated and in a series of adenocarcinomas, including such as in breast cancer and non-small cell lung cancer." (PMID 32877369, 2020). "Moreover, the expression of CDK6 has been downregulated in EA-treated human breast cancer cell lines." (PMID 32429317, 2020). "Interestingly, in one of these multifocal breast cancers, the focus with high-level of CDK6 amplification responded poorly to neo-adjuvant chemotherapy, while the other focus without this amplification showed a complete pathological response." (PMID 32210163, 2020). "Moreover, research focusing on genetic epidemiology has uncovered that the host variations in CDK6 contribute to different clinical outcomes among breast cancer patients, which highlights the importance of the study on genetic susceptibility." (PMID 30829464, 2019). "Perhaps, the prediction of the CDK4/6 inhibitor sensitivity could determine the levels of CDK4 and CDK6 in breast cancer." (PMID 31448056, 2019). "In addition, both MET and CDK6 amplification have been described to contribute to trastuzumab resistance in HER2-overexpressing breast cancer." (PMID 31803359, 2019). "In year 2013, FDA approved CDK4 and CDK6 inhibitors for breast cancer as breakthrough therapies." (PMID 28241745, 2017). "Overall these data indicate that abemaciclib is a CDK4 and CDK6 inhibitor that, as a single agent, blocks breast cancer cell progression, and upon longer treatment can lead to sustained antitumor effects through the induction of senescence, apoptosis, and alteration of cellular metabolism." (PMID 29050219, 2017). "Moreover, in ER+ breast cancer cells, the resistance to fulvestrant was due to the modulated expression of GPER and CDK6 in which the deacetylase was implicated." (PMID 28423597, 2017). "miR-222-3p can also trigger malignant transformation by altering the expression levels of genes involved in cell death and survival, such as CAV2, PTEN, FOXO3, CDK6 and promote aggressive ER-negative breast tumors by increasing proliferation and migratory activity of breast cancer cells." (PMID 27833082, 2016). "In tumors, CDK4 and CDK6 may be selectively required for oncogenic proliferation as described for CDK4 in breast cancer and melanoma, or CDK6 in MLL-rearranged acute myeloid leukemia (AML)." (PMID 27323399, 2016). "Furthermore, as an oncogene, CDK6 can promote tumor cell proliferation and is widely deregulated in different cancers, such as breast cancer, glioma, blastoma, lymphoma and melanoma." (PMID 27230400, 2016). "It is noteworthy that an inhibitor of the essential non-mutated cell cycle regulatory enzymes, CDK4 and CDK6, palbociclib, was recently found to double the progression-free survival of breast cancer patients without causing excessive toxicity." (PMID 26221874, 2015). "An interaction between DLC1 and CDK6 was found to affect breast cancer survival." (PMID 25425654, 2014).